TIPE2 (TNF alpha induced protein 8 like 2)
Diseases named in the same sentence as TIPE2 in open-access papers (continued):
Sharing a sentence is not in itself a finding about the gene and the disease.
tumor (continued). "Additionally, western blot data showed that gracillin induced the cleavage of PARP and expression of TIPE2, and inhibited the phosphorylation of AKT and expression of bcl-2 in the tumor tissue of mice." (PMID 34630074, 2021). "In addition, TIPE2 served as an immunohistochemical biomarker for predicting the prognosis of PDAC patients and assessing the degree of tumor malignancy." (PMID 33850476, 2021). "The results demonstrated that Tipe2 might play dual function in CRC by inducing senescence: suppresses the proliferation and survival of tumor cells but accelerates the initiation of AOM/DSS-induced CRC." (PMID 34702807, 2021). "Therefore, our data indicated that although TIPE2 expression was upregulated in early PDAC tissues, TIPE2 was recognized as a tumor suppressor in PDAC." (PMID 33850476, 2021). "Further, in the case of NSCLC tissues, TIPE2 was found to be upregulated, which exerted a negative correlation with primary tumor size, lymph node metastasis, and advanced clinical stage of the disease." (PMID 31817720, 2019). "All these results demonstrated that TIPE2 could serve as a promising biomarker for the diagnosis of PTC and the prediction of tumor invasiveness." (PMID 30186591, 2018). "The predictive accuracy of TIPE2 expression to distinguish between patients with and without tumor infiltration was accessed using ROC curve." (PMID 30186591, 2018). "All these data suggested that TIPE2 could serve as a promising biomarker for the diagnosis of NSCLC and prediction of tumor metastasis." (PMID 27556698, 2016). "Furthermore, there was a negative correlation between TIPE2 expression and lymph node invasion and tumor metastases." (PMID 40060230, 2025). "This analysis showed that the content of either PE (plasm-18:0/20:4), PE (plasm-18:0/22:4), or PE (18:0/22:6), but not PE (18:0/20:4) and PE (18:0/22:4), was lower in TIPE2−/− tumor MDSCs than in WT tumor MDSCs (where plasm indicates plasmalogens or PUFA-ePLs)." (PMID 39851538, 2025). "However, the function of TIPE2 in EOC and the relationship between TIPE2 and tumor immunity in EOC is largely unknown." (PMID 36801818, 2023). "NK cells expressed higher levels of both T‐bet and Eomes in the absence of TIPE2 than in the presence of TIPE2, suggesting that TIPE2 expression might suppress T‐bet and Eomes expression in tumor‐infiltrating NK cells." (PMID 36807566, 2023). "Therefore, to confirm our results, TGF-β/Smad3 signaling pathway was detected in primary and tumor cell lines transfected with or without Tipe2 plasmid." (PMID 34702807, 2021). "We found that the total tumor number of AOM/DSS-induced CRC from Tipe2+/+ mice was higher than that from Tipe2-/-, especially in tumors with greater diameter more than 2 mm, suggesting that the occurrence of AOM/DSS-induced CRC in Tipe2+/+ mice was probably earlier than that in Tipe2-/- mice." (PMID 34702807, 2021). "However, the expression and roles of TIPE2 in GIST, a special kind of mesenchyme originated neoplasm, are largely unknown." (PMID 30534358, 2018). "No alteration on Ki-67 expression was detected regardless of TIPE2 over-expression, by which we speculated that TIPE2 inhibits tumor growth mainly attributing to its function of promoting apoptosis of H446 cells, but not via affecting proliferation." (PMID 25946186, 2015). "Our previous researches have showed that human TIPE2 was downregulated in tumor tissues of HCC compared with the paired adjacent non-tumorous tissues, suggesting it may be associated with HCC." (PMID 24274578, 2013). "Taken together, we indicate that TIPE2, unlike other members of TIPE family as oncogene in various cancers, is a tumor suppressor, at least in HCC." (PMID 24274578, 2013).
cancer (35 papers, 2013 to 2026). A tumor composed of atypical neoplastic, often pleomorphic cells that invade other tissues. "TIPE2 expression demonstrated a significant correlation with the infiltration of various immune cell populations across most cancers and exhibited strong associations with the expression of immune checkpoint genes." (PMID 41993135, 2026). "Using multiomics data from public databases such as TCGA, GTEx, and HPA, we systematically analyzed TIPE2 expression patterns, genetic and epigenetic alterations, and their associations with clinical outcomes and immune characteristics across 33 cancer types." (PMID 41993135, 2026). "TIPE2 expression was significantly associated with a lower cancer stage and a low metastatic rate (P=0.013 & 0.003, respectively)." (PMID 40060230, 2025). "Studies have shown that TIPE2 causes significant malignant biological effects and is differentially expressed in various malignant tumors." (PMID 33850476, 2021). "Tipe2-deficiency is less susceptible to senescence and might be a checkpoint for immunotherapy against cancer and other age-related diseases." (PMID 34702807, 2021). "The mutational status of TIPE2 in tissues of different NSCLC cancer patients was studied." (PMID 31817720, 2019). "Similarly, in colon cancer tissues, TIPE2 expression is positively associated with lymph node metastases and the Duke stage of cancer." (PMID 30586922, 2018). "In this study, we comprehensively characterized the pan-cancer landscape of TIPE2 and evaluated its potential significance for prognosis and immunotherapy-related stratification." (PMID 41993135, 2026). "TIPE2 is involved in tumorigenesis via different signaling pathways, and its precise role in cancers remains to a great extent obscure." (PMID 40060230, 2025). "TIPE2 was stained in the cytoplasm and nucleus of cancer cells, while CD36 was stained in the membrane with or without cytoplasmic expression of cancer cells." (PMID 40060230, 2025). "TIPE2 has exhibited its powerful role as a new biomarker and therapeutic target in different cancers." (PMID 40060230, 2025). "The TIPE2 (tumor necrosis factor-alpha-induced protein 8-like 2) and programmed cell death ligand 1 (PD-L1) proteins significantly regulate cancer and inflammatory diseases." (PMID 37375246, 2023). "To explore the significance of TIPE2 in cancers, we first analyzed the subcellular localization of TIPE2." (PMID 36187930, 2022). "Subsequent studies have found that TIPE2 is also involved in multiple signaling pathways of tumorigenesis and development, and plays a key role in different processes of cancer cell survival, proliferation, migration and invasion." (PMID 35388275, 2022). "We previously identified TIPE2 as a new therapeutic target for cancer immunotherapy since it plays a critical role in the functional polarization of MDSCs." (PMID 34887765, 2021). "This greatly expanded the available inhibitors for TIPE2, which is a potential novel drug target related to cancer and inflammation." (PMID 34887765, 2021). "Tumor necrosis factor-α-induced protein 8-like 2 (TIPE2), a novel immunoregulatory protein, has been extensively studied in inflammatory response, apoptosis, and cancer." (PMID 33815396, 2021). "The TIPE2 (tumor necrosis factor-alpha-induced protein 8-like 2) protein is a major regulator of cancer and inflammatory diseases." (PMID 34887765, 2021). "Most reports believe that TNFAIP8 and TIPE3 have antiapoptotic and tumorigenesis effects, while TIPE1 and TIPE2 have pro-apoptotic and antitumor effects in most cancers." (PMID 34925463, 2021). "The proportion and the staining intensity of TIPE2-positive cells were obviously lower in carcinoma than in paracancerous tissue." (PMID 34249724, 2021). "TIPE2 in cancer tissues was significantly lower than that in normal tissues (57.5% vs. 87.5%, χ2=9.028, P=0.003)." (PMID 33817189, 2019).
cancer (continued). "Over the last several years, a few studies have been carried out to evaluate the potential of TIPE2 as a clinical biomarker against different cancer types." (PMID 31817720, 2019). "The protein level of TIPE2 was significantly lower in cancer tissues than in adjacent normal tissue (P<0.01)." (PMID 33817189, 2019). "In recent years, increasing studies have demonstrated that TIPE2 plays an inhibitory role in human cancer development." (PMID 31661000, 2019). "One of the greatest challenge for the treatment of GISTs in clinics is chemoresistance, the role of TIPE2 in the chemoresistance and its related mechanisms (such as its effect on cancer stem-like cells etc.)warrant further study." (PMID 30534358, 2018). "Abnormal TIPE2 expression exists in patients with chronic inflammatory diseases and cancers, and correlates with the progression of diseases, which suggests that TIPE2 plays important roles in neoplastic and inflammatory diseases." (PMID 28851386, 2017). "At present, abnormal expression of TIPE2 mRNA and/or protein has been found in several chronic inflammatory diseases and cancers." (PMID 28851386, 2017). "A few studies on the relationship of TIPE2 with cancer already verified TIPE2 had some function in cancer development." (PMID 25946186, 2015). "In positive cancer cells, TIPE2 staining was predominantly found in the cytoplasm but seldom in nuclear." (PMID 25946186, 2015). "Recent studies already revealed that TIPE2 expression were significantly correlated with some cancers such as RCC and HCC." (PMID 25946186, 2015). "Collectively, these findings identify TIPE2 as an immune-relevant biomarker candidate with prognostic significance across various cancers and warrant further mechanistic and clinical validation to elucidate its potential role in immunotherapy-based patient stratification." (PMID 41993135, 2026). "On the other hand, prior studies have demonstrated that TIPE2 inhibits the EMT in other cancers." (PMID 40060230, 2025). "However, there are still many challenges in specifically targeting TIPE2 in MDSCs in a cancer treatment clinical setting." (PMID 39851538, 2025). "TIPE2 has been studied for its potential utility as a biomarker in various cancer types." (PMID 36801818, 2023). "TIPE2 somehow functions as a biological link between cancer and inflammation." (PMID 36801818, 2023). "As a negative regulator of inflammation and immune function, TIPE2 is involved in tumorigenesis and development through a variety of signaling pathways, and its detailed function in cancers remains largely unknown." (PMID 35388275, 2022). "Preceding studies have established TIPE2 reveals vital roles in inflammation and cancer." (PMID 34249724, 2021). "Accelerating evidence indicates that TIPE2 inhibits the development of a variety of malignant tumors by suppressing cell proliferation, inducing cancer cell apoptosis, inhibiting tumor migration, and promoting antitumor immune responses mediated by CD8+ T and natural killer (NK) cells." (PMID 33815396, 2021). "Therefore, inhibiting TIPE2 in certain cell types has the potential to treat certain cancers, e.g., lung cancer." (PMID 34887765, 2021). "They presented widespread mucous glands destruction and derangement, epithelial atypia proliferation, while Tipe2 knockout could alleviate cancer atypia and inflammation." (PMID 34702807, 2021). "On the other hand, in the early stages of cancer, the body may stimulates antitumor immune responses, resulting in an increased TIPE2 level." (PMID 33850476, 2021). "This indicates that inhibitors of TIPE2 may exert an anti-cancer effect through MDSCs, and hence, it would be medically meaningful to discover TIPE2 inhibitors." (PMID 34887765, 2021). "TIPE2 could suppress the proliferation and migration of cancer cells by inhibiting phosphorylation of Erk1/2." (PMID 33817189, 2019).
cancer (continued). "Recently, TIPE2 has been found to be involved in various of epithelium derived carcinomas." (PMID 30534358, 2018). "Increasing studies have been focused on TIPE2 and human cancers in recent years." (PMID 25946186, 2015). "Recent studies found that TIPE2 was involved in cancer development." (PMID 25946186, 2015). "The results from mice suggest that TIPE2 is not only involved in inflammation but also in cancer." (PMID 24274578, 2013). "Upregulation of TIPE2 expression in RCC patients may cause an abnormal resistance to apoptosis, which would ultimately lead to cancer." (PMID 24137373, 2013). "In addition, Formal searches have stated that TIPE2 may reverse the EMT process leading to the suppression of the metastatic ability of cancer endometrium through direct binding to β-catenin." (PMID 40060230, 2025). "TIPE2 has been recently shown to regulate the functional polarization of myeloid-derived suppressor cells (MDSCs) and maybe a potential therapeutic target for cancer immunotherapy." (PMID 33815396, 2021). "However, the expression of TIPE2 mRNA was decreased in advanced cancer (P<0.01)." (PMID 33850476, 2021). "Therefore, if TIPE2 is used as a target for development of new drugs, it may also need to consider whether specific types of cancers can benefit from treatment." (PMID 33817189, 2019). "However, information about TIPE2 in human cancer is limited." (PMID 25946186, 2015). "Targeting TIPE2 in MDSCs not only induces MDSC sensitivity to ferroptosis, but also removes the immunosuppressive TME, thereby further enhancing cancer ferroptotic therapy." (PMID 39851538, 2025). "TIPE2, a member of the same family, suppresses OVCA metastasis and epithelial–mesenchymal transition by interacting with SMAD2, indicating that our findings need to be experimentally validated for the role of TIPE3 in promoting cancer." (PMID 40343258, 2025). "Additionally, our study suggests that the triple combination of targeting the TIPE2 of MDSCs, ferroptosis induction, and ICB therapy is a novel therapeutic option for cancer treatment." (PMID 39851538, 2025). "Tumor necrosis factor-α inducible protein-8 (TIPE2), initially recognized as a negative immune regulator, exerts an important role in suppressing the progression of numerous cancers." (PMID 34630074, 2021). "In addition, knockout of TIPE2 resulted in the downregulation of CXCR-4 and MMP-9, which are involved in the invasion, migration, and metastasis of cancer cells." (PMID 31817720, 2019). "Existing studies have shown that the expression patterns of TIPE2 in different cancers are not consistent." (PMID 33817189, 2019). "Unlike TIPE2, TIPE1 is expressed in various mouse tissues except for mature B and T lymphocytes and in most human carcinoma cell lines." (PMID 31179241, 2019). "Furthermore, to detect whether Rac1 is also required for TIPE2 TCM-mediated inhibition of angiogenesis, we examined the proliferation, migration and tube formation capacity of HUVECs treated with TCM derived from mock, wild type TIPE2, and mutant TIPE2 plasmid transfected cancer cells, respectively." (PMID 27556698, 2016).
infection (6 papers, 2016 to 2023). The state of being infected such as from the introduction of a foreign agent such as serum, vaccine, antigenic substance or organism. "In THP-1 cells, TIPE2 expression was inhibited by MP in a dose-dependent manner, featured by an significant decrease at 2 h post-infection and persisted low-expression at least 24 h after MP infection." (PMID 29042627, 2017). "A significant decrease of TIPE2 mRNA expression was observed in peripheral blood mononuclear cells (PBMCs) from MP patients, which was correlated with the severity of infection." (PMID 29042627, 2017). "In Raw264.7 cells and primary peritoneal macrophages down-regulation for TIPE2 was also observed after infection of MP." (PMID 29042627, 2017). "It was also reported that TIPE2 in the porcine alveolar macrophages (PAMs) was significantly decreased at 12 h post-infection with porcine reproductive and respiratory syndrome virus (PRRSV)." (PMID 27029075, 2016). "In innate immunity against infections, TIPE2 has been reported to reduce phagocytosis and oxidative burst and may be targeted to effectively resist bacterial infections." (PMID 33815396, 2021). "During infection, TIPE2 could inhibit phagocytosis and oxidative burst by binding to and blocking Rac GTPases." (PMID 27696294, 2016). "The expression of TIPE2 mRNA was downregulated after VSV infection and continued to decrease within the infection time of 0–9 h, then increased after 9 h in RAW264.7, THP-1 cell line, and primary peritoneal macrophages." (PMID 33815396, 2021).
inflammation (3 papers, 2018 to 2023). Aberrant reaction of the microcirculation characterized by movement of fluid and leukocytes from the blood into extravascular tissues. "The results showed that TIPE2 was expressed less in AIH mice, whereas in the case of concanavalin A-induced AIH, TIPE2-deficient mice exhibited enhanced levels of serum ALT, AST, pro-inflammatory cytokines, and severe hepatic inflammation." (PMID 30274259, 2018). "TIPE2 overexpression can alleviate LPS-induced lung inflammation and lung cell apoptosis in mice." (PMID 37069964, 2023).
immune diseases (2 papers, 2022). "The new mechanism of TIPE2 inducing cellular immune disorders provides new strategy for elucidating the relevant molecular signaling mechanism, the treatment and prognosis of hemorrhagic shock." (PMID 35572554, 2022). "It has been reported that the expression of TIPE2 is dysregulated in several types of human immune diseases." (PMID 35528518, 2022). "Increasing evidences reveal that the downregulation of TIPE2 in CD4+ T cells enable the animals resistant to immune disorders by reducing the expression levels of apoptotic genes and immunosuppressive factors." (PMID 35572554, 2022). "This may be related to PHSML-induced CD4+ T cells immune dysfunction, resulting in TIPE2 losing normal immune regulatory function, and the related mechanism needs to be further studied." (PMID 35572554, 2022). "In our experiments, TIPE2 was used as an intervention target to modulate PHSML-induced cellular immunosuppression, providing new insights into the regulation of immune disorders after hemorrhagic shock." (PMID 35572554, 2022). "TIPE2 improves the PHSML-mediated CD4+T cells dysfunction by regulating TLR2/TLR4 pathway, providing a new intervention target following hemorrhagic shock-induced immune dysfunction." (PMID 35572554, 2022).
endocrine disorders (1 paper, 2022). "According to the distribution of TIPE2 in systemic tissues, we speculated that TIPE2 inhibitors may have some side effects such as immune-related pneumonia, endocrine disorders, various types of digestive tract discomfort, and symptoms associated with a cytokine storm." (PMID 36187930, 2022).
TIPE2 also shares sentences with these, for which no sentence is quoted: hepatitis B (3 papers); melanoma (3); adenocarcinoma (2); type 2 diabetes mellitus (2); Acute hepatitis (1); acute lung injury (1); acute myeloid leukemia (1); allergic disease (1); bacterial infections (1); cardiovascular disease (1); childhood asthma (1); chromophobe renal cell carcinoma (1); COVID-19 (1); endometrial cancer (1); glioblastoma multiforme (1); head and neck cancer (1); heart failure (1); hypertrophy (1); infectious disease (1); large cell carcinoma (1); large cell lung carcinoma (1); leukocytosis (1); Lewis lung carcinoma (1); listeriosis (1); liver cancer (1); lung squamous cell carcinoma (1); lymphoma (1); mycoplasma pneumonia (1); non-Hodgkin lymphoma (1); osteosarcoma (1).
A further 5 diseases each share a sentence with TIPE2 in 1 paper.